MRPS31P5 (mitochondrial ribosomal protein S31 pseudogene 5)
Synonyms: formerly MRPS31P3
Gene: Transcribed unprocessed pseudogene on chromosome 13 (52,175,639 to 52,194,378, reverse strand). Ensembl gene ENSG00000243406.
Diseases named in the same sentence as MRPS31P5 in open-access papers:
MRPS31P5 is named in the same sentence as 2 diseases in open-access papers, as found by Europe PMC text mining. Sharing a sentence is not in itself a finding about the gene and the disease. The quoted sentences say what the papers report.
cancer (1 paper, 2020). A tumor composed of atypical neoplastic, often pleomorphic cells that invade other tissues. "Interestingly, our RNA-Seq data showed that MRPS31P5, MDM4 and THBD were expressed at significantly higher levels only in cancer tissues, while PCNXL3 did not result to be differentially expressed." (PMID 32992457, 2020).
tumor (1 paper, 2020). "At a molecular level, we found that three individuals shared a tumor-specific fusion named MRPS31-SUGT1, generated through an intra-chromosomal translocation on chromosome 13, whose sequence resulted in being 100% identical to the long non-coding RNA (lncRNA) MRPS31P5." (PMID 32992457, 2020).